ITIH1 (inter-alpha-trypsin inhibitor heavy chain 1)
Diseases named in the same sentence as ITIH1 in open-access papers (continued):
Sharing a sentence is not in itself a finding about the gene and the disease.
tumor (16 papers, 2008 to 2025). "It is well-known that the immune microenvironment plays key roles both in tumor progression and elimination, therefore it is interesting to analyze the association between ITIH1 expression and the pro-/anti-tumor immune components." (PMID 33744857, 2021). "We also explored the genomic alterations of ITIH1 and the associations of ITIH1 expression with tumor immune activities across different cancer types." (PMID 33744857, 2021). "We found that the ITIH1 protein level was decreased in tumor tissues, while the levels of pFAK (Tyr397) and pSRC (Tyr416) were increased in tumor tissues." (PMID 39234824, 2024). "Four weeks after treatment, the nude mice were sacrificed, and H&E staining and imaging showed that the tumor volume in the galunisertib+r‐ITIH1 group decreased more significantly than that in the other groups." (PMID 39234824, 2024). "Since ITIH1 is a secreted protein located in the extracellular matrix, we then used purified ITIH1 (recombinant ITIH1, r‐ITIH1) to evaluate the tumor suppressive effect in vivo." (PMID 39234824, 2024). "To evaluate the tumor‐suppressive role of ITIH1 in HCC in vivo, we applied various xenograft models." (PMID 39234824, 2024). "In summary, these data indicated that ITIH1 acts as a tumor suppressor during HCC progression." (PMID 39234824, 2024). "In another HCC patient‐derived xenograft (PDX) model, r‐ITIH1 was injected near the tumor." (PMID 39234824, 2024). "Indeed, an in vivo experiment has already shown that the number of tumor metastases significantly decreased upon ITIH1 and ITIH3 overexpression." (PMID 33744857, 2021). "In addition, we analyzed the correlation between ITIH1 expression and TMB (Tumor mutational burden)/MSI (Microsatellite instability) across 33 cancer types." (PMID 33744857, 2021). "Since tumor progression is tightly associated with re-arrangement of the extracellular matrix, employment of AMBP, ITIH1, and ITIH4 may also support the net benefit for early detection of CRC and designation of probable cell migration." (PMID 32023884, 2020). "This process might explain why we detected lower ITIH1 expression in HCC tumor tissues." (PMID 39234824, 2024). "Moreover, using the TIDE (Tumor Immune Dysfunction and Exclusion) database, we found that ITIH1 expression was also negatively correlated to T cell exclusion signatures, including FAP+ CAFs, myeloid-derived suppressor cells (MDSC), and tumor-associated M2 macrophages (TAM M2)." (PMID 33744857, 2021). "Our results showed that ITIH1 was significantly down-regulated in LIHC, and its expression was closely related to tumor stage and survival." (PMID 33744857, 2021). "We also observed that the expression levels of ITIH1, ITIH3, and ITIH4 increased with tumor staging of KIRC patients, as did that of ITIH2 in KIRP patients." (PMID 33744857, 2021). "Given that ITIH1 was significantly down-regulated in LIHC and closely correlated with both tumor grade and patient outcome, we decided to determine its potential functional role in cancers." (PMID 33744857, 2021). "Significant alterations in Inter-alpha-trypsin inhibitor heavy chains (ITIH1, ITIH2, ITIH3, and ITIH4) levels were also observed due to their implication in tumor growth and the malignancy process." (PMID 32023884, 2020). "Considering the crucial role of T cells in tumor killing, we further conducted flow cytometry analysis on T cell subsets and found that CD8+ T cells in the T cell population had a higher abundance in the tumors after overexpressing ITIH1." (PMID 39234824, 2024). "Interestingly, each member of the ITIH gene family except ITIH1 (data not shown) exhibited highly differential expression in a remarkable number of human tumor entities." (PMID 18226209, 2008).
tumor (continued). "However, the unique enrichment of glypican‐1, syndecan‐1, ITIH1 and other tumor‐promoting factors in supermeres, many of which were conserved between GBM and CRC, suggests that supermeres may serve as broadly conserved vehicles for modulating the tumor microenvironment across cancer types." (PMID 41039818, 2025).
cancer (9 papers, 2008 to 2025). A tumor composed of atypical neoplastic, often pleomorphic cells that invade other tissues. "Our results showed that the mutation frequencies of ITIH1 in cancers appeared to be quite low, and the main mutation type was missense mutation." (PMID 33744857, 2021). "We observed that the overall mutation rate of ITIH1 in cancers is relatively low (less than 10%)." (PMID 33744857, 2021). "In addition, we studied the gene expression signatures associated with ITIH1 in order to gain further insight into the biologic importance of ITIH1 expression in cancers." (PMID 33744857, 2021). "Herein, we used seven algorisms (TIMER, EPIC, MCPCOUNTER, CIBERSORT, CIBERSORT−ABS, QUANTISEQ, and XCELL) to quantify the density of CD8+ T cells in each cancer type, which, were then correlated to ITIH1 expression levels." (PMID 33744857, 2021). "Using the GSCA database, we further examined the correlation between ITIH1 DNA methylation and expression in pan-cancers." (PMID 33744857, 2021). "Strikingly, we found that for most cancers ITIH1 significantly correlated with checkpoint genes in a positive direction except for LIHC in a negative direction." (PMID 33744857, 2021). "We observed an overall positive correlation between the fraction of CD8+ T cells and ITIH1 expression in pan-cancers except for that of CHOL, where the two components were negatively correlated based on all the algorisms." (PMID 33744857, 2021). "To further assess the role of ITIH1 in tumors, we derived genes that were significantly co-expressed with it across pan-cancers (r > 0.4)." (PMID 33744857, 2021). "Our analyses demonstrated that ITIH1 expression and CAFs abundances were positively correlated in most cancer types." (PMID 33744857, 2021). "Finally, our findings shed light on the functional role of ITIH1 in cancers, suggesting a strong correlation between ITIH1 expression and metabolic pathways." (PMID 33744857, 2021). "Therefore, it will be of great interest to determine the functional relationship between ITIH1 expression and cancer glycolysis metabolism in LIHC." (PMID 33744857, 2021). "No hot spot mutation site was detected for ITIH1 in pan-cancers." (PMID 33744857, 2021).
infection (3 papers, 2019 to 2026). The state of being infected such as from the introduction of a foreign agent such as serum, vaccine, antigenic substance or organism. "ITIH1 is likely to be involved in this process, as ITIH1‐mediated alterations in the cross‐linking state of hyaluronic acid markedly influence extracellular matrix permeability and thereby modulate the rate of inflammatory cell migration toward sites of infection." (PMID 41477556, 2026). "In this study, ITIH1, ITIH2, were found to be negative acute phase reactants while ITIH3, and ITIH4 acted as positive acute phase proteins during both infection types in NHPs." (PMID 30774579, 2019).
bacterial infection (1 paper, 2025). "This discrepancy may reflect the more severe illness of patients in our cohort (septic shock versus bacterial infection), leading to lower ITIH1 levels." (PMID 40885913, 2025). "Patients with bacterial infection had lower plasma levels of AMBP and ITIH2, an increase in ITIH3, while ITIH1 remained unchanged compared with healthy controls." (PMID 40885913, 2025).
ITIH1 also shares sentences with these, for which no sentence is quoted: breast carcinoma (2 papers); diabetes (2); adenoma (1); Alzheimer disease (1); autism spectrum disorder (1); autoimmune disease (1); colon cancer (1); depression (1); diabetic retinopathy (1); esophagus cancer (1); Hypoglycemia (1); Impaired glucose tolerance (1); lipoma (1); liver cancer (1); major depressive disorder (1); mesothelioma (1); mood disorder (1); non-Hodgkin lymphoma (1); ovarian serous cystadenocarcinoma (1); pancreatic cancers (1); prostate adenocarcinoma (1); psychotic disorder (1); rectum adenocarcinoma (1); renal cell carcinoma (1); uterine cancer (1); uterine corpus endometrial carcinoma (1).